CUL3 (cullin 3)
Description:
Core component of multiple cullin-RING-based BCR (BTB-CUL3-RBX1) E3 ubiquitin-protein ligase complexes which mediate the ubiquitination and subsequent proteasomal degradation of target proteins. BCR complexes and ARIH1 collaborate in tandem to mediate ubiquitination of target proteins. As a scaffold protein may contribute to catalysis through positioning of the substrate and the ubiquitin-conjugating enzyme. The E3 ubiquitin-protein ligase activity of the complex is dependent on the neddylation of the cullin subunit and is inhibited by the association of the deneddylated cullin subunit with TIP120A/CAND1. The functional specificity of the BCR complex depends on the BTB domain-containing protein as the substrate recognition component. BCR(KLHL42) is involved in ubiquitination of KATNA1. BCR(SPOP) is involved in ubiquitination of BMI1/PCGF4, BRMS1, MACROH2A1 and DAXX, GLI2 and GLI3. Can also form a cullin-RING-based BCR (BTB-CUL3-RBX1) E3 ubiquitin-protein ligase complex containing homodimeric SPOPL or the heterodimer formed by SPOP and SPOPL; these complexes have lower ubiquitin ligase activity. BCR(KLHL9-KLHL13) controls the dynamic behavior of AURKB on mitotic chromosomes and thereby coordinates faithful mitotic progression and completion of cytokinesis. BCR(KLHL12) is involved in ER-Golgi transport by regulating the size of COPII coats, thereby playing a key role in collagen export, which is required for embryonic stem (ES) cells division: BCR(KLHL12) acts by mediating monoubiquitination of SEC31 (SEC31A or SEC31B). BCR(KLHL3) acts as a regulator of ion transport in the distal nephron; by mediating ubiquitination of WNK4. The BCR(KLHL20) E3 ubiquitin ligase complex is involved in interferon response and anterograde Golgi to endosome transport: it mediates both ubiquitination leading to degradation and 'Lys-33'-linked ubiquitination. The BCR(KLHL21) E3 ubiquitin ligase complex regulates localization of the chromosomal passenger complex (CPC) from chromosomes to the spindle midzone in anaphase and mediates the ubiquitination of AURKB. The BCR(KLHL22) ubiquitin ligase complex mediates monoubiquitination of PLK1, leading to PLK1 dissociation from phosphoreceptor proteins and subsequent removal from kinetochores, allowing silencing of the spindle assembly checkpoint (SAC) and chromosome segregation. The BCR(KLHL22) ubiquitin ligase complex is also responsible for the amino acid-stimulated 'Lys-48' polyubiquitination and proteasomal degradation of DEPDC5. Through the degradation of DEPDC5, releases the GATOR1 complex-mediated inhibition of the TORC1 pathway. The BCR(KLHL25) ubiquitin ligase complex is involved in translational homeostasis by mediating ubiquitination and subsequent degradation of hypophosphorylated EIF4EBP1 (4E-BP1). The BCR(KLHL25) ubiquitin ligase complex is also involved in lipid synthesis by mediating ubiquitination and degradation of ACLY. The BCR(KBTBD8) complex acts by mediating monoubiquitination of NOLC1 and TCOF1, leading to remodel the translational program of differentiating cells in favor of neural crest specification. Involved in ubiquitination of cyclin E and of cyclin D1 (in vitro) thus involved in regulation of G1/S transition. Involved in the ubiquitination of KEAP1, ENC1 and KLHL41. In concert with ATF2 and RBX1, promotes degradation of KAT5 thereby attenuating its ability to acetylate and activate ATM. The BCR(KCTD17) E3 ubiquitin ligase complex mediates ubiquitination and degradation of TCHP, a down-regulator of cilium assembly, thereby inducing ciliogenesis. The BCR(KLHL24) E3 ubiquitin ligase complex mediates ubiquitination of KRT14, controls KRT14 levels during keratinocytes differentiation, and is essential for skin integrity. The BCR(KLHL18) E3 ubiquitin ligase complex mediates the ubiquitination of AURKA leading to its activation at the centrosome which is required for initiating mitotic entry. The BCR(KEAP1) E3 ubiquitin ligase complex acts as a key sensor of oxidative and electrophilic stress by mediating ubiquitination and degradation of NFE2L2/NRF2, a transcription factor regulating expression of many cytoprotective genes. As part of the CUL3(KBTBD6/7) E3 ubiquitin ligase complex functions mediates 'Lys-48' ubiquitination and proteasomal degradation of TIAM1. By controlling the ubiquitination of that RAC1 guanine exchange factors (GEF), regulates RAC1 signal transduction and downstream biological processes including the organization of the cytoskeleton, cell migration and cell proliferation. The BCR(KBTBD4) E3 ubiquitin ligase complex targets CoREST corepressor complex components RCOR1, KDM1A/LSD1 and HDAC2 for proteasomal degradation with RCOR1 likely to be the primary target while degradation of KDM1A and HDAC2 is likely due to their association with RCOR1. It also targets RCOR3, MIER2 and MIER3 for proteasomal degradation as well as associated proteins ZNF217 and RREB1 with degradation being dependent on the presence of an ELM2 domain in the target proteins. The BCR(ARMC5) complex mediates premature transcription termination of transcripts that are unfavorably configured for transcriptional elongation by mediating ubiquitination of Pol II subunit POLR2A. Required for 'Lys-63'-linked ubiquitination of large ribosomal subunit protein MRPL12. Protects against human enterovirus D68 infection by mediating the ubiquitination and subsequent degradation of viral protein VP1.
Synonyms: CUL-3; NEDAUS; PHA2E
Tractability: Antibody: its Gene Ontology location is reachable by antibodies, with high confidence. PROTAC: UniProt records ubiquitination sites on it; ubiquitination databases record sites on it; its protein half-life has been measured.
Gene: Protein-coding gene on chromosome 2 (224,470,150 to 224,585,397, reverse strand). Ensembl gene ENSG00000036257.
Subcellular location: Nucleus; Golgi apparatus; Cell projection, cilium, flagellum; Cytoplasm, cytoskeleton, spindle; Cytoplasm; Cytoplasm, cytoskeleton, microtubule organizing center, centrosome; Cytoplasm, cytoskeleton, spindle pole
Subcellular location (Human Protein Atlas): Nucleoplasm; Cytokinetic bridge; Microtubules
Pathways (Reactome):
Signal Transduction: Degradation of DVL; Hedgehog 'on' state; RHOBTB1 GTPase cycle; RHOBTB2 GTPase cycle; RHOBTB3 ATPase cycle; Regulation of RAS by GAPs
Immune System: Antigen processing: Ubiquitination & Proteasome degradation; SPOP-mediated proteasomal degradation of PD-L1(CD274)
Cellular responses to stimuli: KEAP1-NFE2L2 pathway
Disease: Potential therapeutics for SARS
Metabolism of proteins: Neddylation
Gene Ontology:
Molecular function: Notch binding; POZ domain binding; protein binding; ubiquitin ligase complex scaffold activity; ubiquitin protein ligase activity; ubiquitin protein ligase binding; ubiquitin-protein transferase activity; cyclin binding; identical protein binding
Biological process: anaphase-promoting complex-dependent catabolic process; cell migration; cellular response to amino acid stimulus; cellular response to oxidative stress; COPII vesicle coating; endoplasmic reticulum to Golgi vesicle-mediated transport; establishment of endothelial barrier; mitotic metaphase chromosome alignment; negative regulation of Rho protein signal transduction; negative regulation of type I interferon production; nuclear protein quality control by the ubiquitin-proteasome system; positive regulation of cilium assembly; positive regulation of cytokinesis; positive regulation of mitotic cell cycle phase transition; positive regulation of mitotic metaphase/anaphase transition; positive regulation of protein K63-linked ubiquitination; positive regulation of protein ubiquitination; positive regulation of TORC1 signaling; proteasome-mediated ubiquitin-dependent protein catabolic process; protein autoubiquitination; protein destabilization; protein K48-linked ubiquitination; protein monoubiquitination; protein polyubiquitination; protein ubiquitination; and 19 more
Cellular component: centrosome; Cul3-RING ubiquitin ligase complex; cytoplasm; extracellular exosome; Golgi apparatus; membrane; microtubule cytoskeleton; mitotic spindle; nucleoplasm; nucleus; plasma membrane; polar microtubule; sperm flagellum; spindle pole; cytosol; cullin-RING ubiquitin ligase complex; glutamatergic synapse; motile cilium; postsynapse; spindle
Genetic constraint (gnomAD): Loss-of-function variants: 14 observed, 59.96 expected, observed/expected ratio (o/e) 0.23, 90% interval 0.15 to 0.37. The upper end of that interval is the gene's LOEUF score, 0.37, which puts it in group 1 of 6, group 1 being the genes least tolerant of losing a copy. Missense variants: 405 observed, 805.77 expected, observed/expected ratio (o/e) 0.5, 90% interval 0.46 to 0.55. Synonymous variants: 308 observed, 269.24 expected, observed/expected ratio (o/e) 1.14, 90% interval 1.04 to 1.26.
Gene-disease validity (ClinGen):
ClinGen rates the evidence that CUL3 causes each of these diseases.
complex neurodevelopmental disorder (autosomal dominant): Definitive. A disorder that involves more than one phenotype associated with the central nervous system, including but not limited to intellectual disability, autism, and seizures (epilepsy).
pseudohypoaldosteronism type 2E (autosomal dominant): Definitive.
Homologues: Orthologues: chimpanzee CUL3 (100% identical), macaque CUL3 (100% identical), rat Cul3 (99% identical), mouse Cul3 (99% identical), tropical clawed frog cul3 (99% identical), guinea pig CUL3 (97% identical), rabbit CUL3 (97% identical), zebrafish cul3b (97% identical), pig CUL3 (97% identical), zebrafish cul3a (96% identical), Drosophila melanogaster Cul3 (69% identical), Caenorhabditis elegans cul-3 (50% identical). Paralogues in human: CUL4A (39% identical), CUL4B (38% identical), CUL1 (30% identical), CUL2 (26% identical), CUL5 (25% identical), ANAPC2 (16% identical), CACUL1 (8% identical).
Diseases named in the same sentence as CUL3 in open-access papers:
CUL3 is named in the same sentence as 142 diseases in open-access papers, as found by Europe PMC text mining. Sharing a sentence is not in itself a finding about the gene and the disease. The quoted sentences say what the papers report.
Hypertension (27 papers, 2014 to 2025). The presence of chronic increased pressure in the systemic arterial system. "The dysregulation of Cullin 3 is associated with various diseases, including cancer, diabetes, hypertension, and hyperkalemia, making it a potential therapeutic target (38, –, 41)." (PMID 40396757, 2025). "Collectively, these findings provide evidence that CUL3-induced hypertension in FHHt is caused by alteration of both renal and vascular mechanisms." (PMID 37845702, 2023). "In this review, we describe the role of CUL3 variants in electrolyte/metabolic imbalances and hypertension in FHHt." (PMID 37845702, 2023). "CUL3 exerts a pivotal role in maintaining the balance of arterial pressure, and loss of its ubiquitin ligase activity is closely implicated in hypertension." (PMID 35715796, 2022). "Research has proposed that CUL3 exerts a pivotal role in maintaining the balance of arterial pressure, and loss of its ubiquitin ligase activity is closely implicated in hypertension." (PMID 35715796, 2022). "Abnormal protein function caused by CUL3 is associated with atherosclerosis, angina pectoris and acute coronary syndrome, and hypertension itself is a key cause of these diseases." (PMID 35715796, 2022). "Mutation of CUL3 can lead to vascular smooth muscle defects, leading to severe vascular dysfunction and hypertension." (PMID 35715796, 2022). "Rats with CUL3 mutations exhibit arterial hypertension, while patients with CUL3 mutations present severe early-onset hypertension, vascular dysfunction, and arterial stiffness due to deficiency of vascular smooth muscle." (PMID 33995494, 2021). "In particular, mutations in CUL3 causes severe hypertension by affecting both renal and vascular function." (PMID 33066544, 2020). "It has been demonstrated that hypertension-causing mutations in CUL3 impair RhoA ubiquitylation and that selective expression of mutant CUL3 in VSMCs results in augmented RhoA signaling and vascular dysfunction, leading to elevation of BP." (PMID 32731518, 2020). "CCCs are also involved in hypothalamic signaling in hypertension and the mutations in the regulatory CUL3/KLHL3-WNK-SPAK/OSR1 pathway contribute to the pathology of FHHt." (PMID 33066544, 2020). "Gordon syndrome subjects with CUL3 mutations have the most severe phenotype and present at a younger age and had more severe hyperkalaemia, hypertension, and metabolic acidosis in addition to growth impairment." (PMID 31795491, 2019). "Mutations in Culin-3 (CUL3) were identified as a cause of hypertension (HTN) in humans." (PMID 40627460, 2025). "In addition to the classical phenotypic triad of hypertension, hyperkalemia, and metabolic acidosis, FHHt patients with CUL3 variants experienced diverse systemic and early developmental disturbances like failure to thrive, malaise, and paralysis." (PMID 37845702, 2023). "Interestingly, conditional loss of Cul3 in primary aortic smooth muscle cells in mice led to an even greater magnitude of hypertension compared to transgenic CUL3Δ403-459 mice." (PMID 37845702, 2023). "While FHHt patients with CUL3, KLHL3 or WNK mutations present with the same disease, those with mutations in CUL3 display a more severe phenotype, evident in terms of both an earlier age-of-onset and the degree of hypertension and electrolyte disturbance reported." (PMID 26286618, 2015). "Also, mutations in another member of the cullin family, CUL3, have been found to cause some Mendelian forms of hypertension." (PMID 24628878, 2014). "In addition to the presented MLN4924-induced RhoA overactivation in cancer cell lines, Mdmx may be involved in conditions such as hypertension or decreased brain size due to Cul3 mutations where RhoA is also found to be overactivated." (PMID 39404389, 2024). "The metabolic pathway of Cullin-3 protein revealed that the derivative is Sulfonamide which play role in, increasing urine output, and metabolic acidosis resulted in hypertension." (PMID 38615119, 2024).
Hypertension (continued). "The biochemical characterization of this novel CUL3 variant in the FHHt patient’s urinary exosome vesicles (uEVs) and cells established the deletion of amino acids 474–477 in exon 10 of CUL3 as the source of electrolyte imbalance and hypertension in vivo." (PMID 37845702, 2023). "In the hypertension phenotype of CUL3-induced FHHt, CUL3-BACURD1-RhoA/ROCK and CUL3-RhoBTB1-PED5-cGMP signaling pathways are associated with increased vasoconstriction and decreased vasodilation, respectively." (PMID 37845702, 2023). "The identification of disease-associated variants in both CUL3 and KLHL3 in PHAII patients highlights the important role of the CUL3-KLHL3 complex in the pathophysiology of electrolyte imbalance and hypertension." (PMID 37845702, 2023). "It has been well reported that mutations in the CUL3 are the direct cause of pseudohypoaldosteronism type II (PHAII), which results in hypertension and hyperkalemia." (PMID 35715796, 2022). "The present study aimed to explore the effects of restoration of CUL3 gene expression on the apoptosis, oxidative stress, proliferation and migration during hypertension as well as its regulation on SHH signaling." (PMID 35715796, 2022). "We will further investigate the upstream mechanism of CUL3 in hypertension, which is the next experimental plan of our study." (PMID 35715796, 2022). "PHA II causing mutations in KLHL3 decreases Wnk4 binding to Cul3-RING ubiquitin ligase, decreasing WNK4 degradation and increasing its levels resulting in hypertension." (PMID 35197862, 2022). "If Gli was overexpressed, insufficient degradation of Gli by CUL3 would lead to excessive proliferation of VSMCs, which would aggravate the pathological conditions of hypertension." (PMID 35715796, 2022). "CUL3 mutations, responsible for a severe form of familial hyperkalemia and hypertension (FHHt), all result in a deletion of exon 9 (amino-acids 403-459) (CUL3-∆9)." (PMID 35563538, 2022). "Mutations in KLHL3 and CUL3 have been implicated in PHA II and appear to cause hypertension and electrolyte disbalance." (PMID 35197862, 2022). "Collectively, restoration of CUL3 gene expression protected against hypertension through enhancing the effects of SHH activation in inhibition of apoptosis and oxidative stress for hypertension and alleviating the dysfunction of VSMCs." (PMID 35715796, 2022). "An increasing number of studies have validated that the regulation of CUL3/Gli balance plays a key role in various physiological and pathological mechanisms hypertension." (PMID 35715796, 2022). "Mutations in WNK1, WNK4, KLHL3, and CUL3 all result in the accumulation of WNK-kinase 4 and subsequent hypertension, hyperkalaemia, and metabolic acidosis." (PMID 31795491, 2019). "The central role of CUL3 in metazoan development, and its frequent misregulation in cancer, autism, or hypertension, implies that this E3 ligase needs to be under strict control." (PMID 29999490, 2018). "Through stabilizing WNK isoforms, the mutation of CUL3 has been linked to Pseudohypoaldosteronism type II (PHAII), a rare Mendelian syndrome featuring hypertension." (PMID 28804198, 2017). "CUL3-related mechanisms in the vasculature that contribute to hypertension appear worthy of pursuit." (PMID 26294796, 2015). "Deletion of exon 9 from Cullin-3 (CUL3, residues 403–459: CUL3Δ403–459) causes pseudohypoaldosteronism type IIE (PHA2E), a severe form of familial hyperkalaemia and hypertension (FHHt)." (PMID 26286618, 2015). "This examination unveiled that Cullin-3's derivative is Sulfonamide, which contributes to structural expansion, heightened urine output, and the development of metabolic acidosis, leading to hypertension." (PMID 38615119, 2024). "Thus, while the WNK-SPAK-NCC pathway is likely pathogenic for the hyperkalemia and metabolic acidosis seen in FHHt patients, the exact mechanism behind the pediatric onset of hypertension in CUL3-induced FHHt has yet to be solidified." (PMID 37845702, 2023).